MMP16 (matrix metallopeptidase 16)
Description:
Endopeptidase that degrades various components of the extracellular matrix, such as collagen type III and fibronectin. Activates progelatinase A. Involved in the matrix remodeling of blood vessels. Isoform short cleaves fibronectin and also collagen type III, but at lower rate. It has no effect on type I, II, IV and V collagen. However, upon interaction with CSPG4, it may be involved in degradation and invasion of type I collagen by melanoma cells.
Synonyms: MT3-MMP; C8orf57; DKFZp761D112; MMP-X2; MT-MMP2; MT-MMP3
Tractability: Small molecule: a structure with a bound ligand is known; a high-quality ligand is known; it belongs to a druggable protein family. Antibody: UniProt places it where antibodies can reach, with high confidence; its Gene Ontology location is reachable by antibodies, with high confidence; UniProt predicts a signal peptide or a membrane-spanning region. PROTAC: a small molecule that binds it is known.
Target class: Metallo protease; Metallo protease M10A subfamily; Metallo protease MAM clan; Protease; Enzyme
Gene: Protein-coding gene on chromosome 8 (88,032,011 to 88,328,025, reverse strand). Ensembl gene ENSG00000156103.
Subcellular location: Cell membrane (Isoform Long); Secreted, extracellular space, extracellular matrix (Isoform Short); Cell surface
Subcellular location (Human Protein Atlas): Cytosol; Vesicles; Predicted to be secreted
Pathways (Reactome):
Extracellular matrix organization: Activation of Matrix Metalloproteinases
Signal Transduction: TGFBR3 PTM regulation
Gene Ontology:
Molecular function: metalloaminopeptidase activity; metalloendopeptidase activity; zinc ion binding; enzyme activator activity; metallopeptidase activity
Biological process: protein processing; proteolysis; collagen catabolic process; extracellular matrix organization; skeletal system development
Cellular component: plasma membrane; Golgi lumen; cell surface; extracellular matrix
Genetic constraint (gnomAD): Loss-of-function variants: 10 observed, 56.81 expected, observed/expected ratio (o/e) 0.18, 90% interval 0.11 to 0.3. The upper end of that interval is the gene's LOEUF score, 0.3, which puts it in group 1 of 6, group 1 being the genes least tolerant of losing a copy. Missense variants: 443 observed, 713.58 expected, observed/expected ratio (o/e) 0.62, 90% interval 0.57 to 0.67. Synonymous variants: 227 observed, 245.3 expected, observed/expected ratio (o/e) 0.93, 90% interval 0.83 to 1.03.
Homologues: Orthologues: macaque MMP16 (100% identical), chimpanzee MMP16 (99% identical), dog MMP16 (99% identical), pig MMP16 (99% identical), rabbit MMP16 (99% identical), rat Mmp16 (98% identical), mouse Mmp16 (98% identical), tropical clawed frog mmp16 (87% identical), guinea pig MMP16 (86% identical), zebrafish mmp16b (72% identical), Caenorhabditis elegans zmp-3 (27% identical), Caenorhabditis elegans zmp-4 (19% identical), and 3 more. Paralogues in human: MMP24 (66% identical), MMP15 (54% identical), MMP14 (53% identical), MMP25 (32% identical), MMP17 (31% identical), MMP1 (31% identical), MMP8 (30% identical), MMP2 (30% identical), MMP3 (30% identical), MMP10 (29% identical), MMP12 (29% identical), MMP13 (29% identical), and 11 more.
Diseases named in the same sentence as MMP16 in open-access papers:
MMP16 is named in the same sentence as 87 diseases in open-access papers, as found by Europe PMC text mining. Sharing a sentence is not in itself a finding about the gene and the disease. The quoted sentences say what the papers report.
glioma (19 papers, 2012 to 2025). A benign or malignant brain and spinal cord tumor that arises from glial cells (astrocytes, oligodendrocytes, ependymal cells). "The membrane-type metalloproteinase MMP16 exhibiting a Y290H mutation mapping to the C-end of the peptidase domain showed similar levels in all samples, consistent with its reported expression in glioma and normal brain." (PMID 33853673, 2021). "MuSK-CAART cytotoxicity was subsequently evaluated against U87-MG glioma cells, which express MMP16 as well as LRP4." (PMID 36658341, 2023). "In this regard, the transfected U87 glioma cells presented shorter protrusions in response to miR-146b-5p mimics; also, direct blocking of MMP-16 using exogenous siRNA restored the miRNA activity against migration and invasion of glioma cells." (PMID 35922753, 2022). "The expression levels of miR-146b-5p in glioma cells are significantly low, while MMP16 show a surge in the same cells." (PMID 35922753, 2022). "Reportedly, MMP16 is overexpressed in melanoma, gastric cancer, and glioma, and its high expression implies the adverse prognosis of the patients." (PMID 34747300, 2021). "Concurrently, MMP16 had the highest expression levels in NB and gliomas, a finding that we confirmed in the present study." (PMID 32872536, 2020). "MiR-146b-5p targets MMP16 to dramatically inhibit glioma and pancreatic cancer migration and invasion." (PMID 31137698, 2019). "This is in concordance with a previous report which showed that decreasing MMP-16 levels efficiently limited cell migration of glioma cells." (PMID 22348515, 2012). "M1-Exo miR-150 inhibits glioma progression by targeting MMP-16 to inhibit human glioma cells." (PMID 39896803, 2024). "miR-146b-5p upregulation leads to MMP16 knockdown, thus hindering glioma cell growth." (PMID 34381502, 2021). "Sevoflurane restrained the metastasis of glioma cells through modulating miR-146b-5p/MMP16 axis." (PMID 33126850, 2020). "Silencing MMP16 expression dramatically inhibit cell migration and invasion of glioma cells." (PMID 27340864, 2016). "In gliomas, reduced expression of miR-146b contributes to increase MMP16 and promote metastasis." (PMID 26883911, 2016). "Our previous study has discovered that miR-146b-5p expression is decreased in gliomas and that miR-146b-5p overexpression may suppress the migration and invasion of glioma cells by directly targeting MMP16." (PMID 26320176, 2015). "In line with this, a recent paper used the TCGA data and found that expression levels of MMP16 and MMP17 in gliomas were in the top two of all cancers." (PMID 32872536, 2020). "The overlapping substrate panels of MT-MMPs, e.g., MMPs15, -16, and -24 are pro-MMP2 activators, suggest that these too might enhance the migration and infiltration of glioma cells; indeed, MMP15 and MMP16 have been demonstrated to enhance glioma cell migration in vitro." (PMID 32872536, 2020). "Since other target genes, such as MMP16 and EGFR, were also involved in the modulation induced by miR-146b-5p, the prognostic significance of TRAF6 was not as important as that of miR-146b-5p in gliomas." (PMID 26320176, 2015).
melanoma (12 papers, 2011 to 2024). A malignant, usually aggressive tumor composed of atypical, neoplastic melanocytes. "In contrast, genes that were commonly downregulated in sensitive and resistant melanoma spheroids, including MMP16, IGF1R and FLOT1, are associated with malignancy, and several studies have reported that these genes are related to the aggressive behaviour of melanoma." (PMID 32613561, 2020). "The effect of MMP16 on cancer progression has been reported in multiple cancers, such as prostate cancer, colon cancer and melanoma, where it promotes migration, invasion, and metastasis." (PMID 32352029, 2020). "In melanoma, MMP16 mediates a proteolytic switch that promotes cell adhesion and lymphatic invasion." (PMID 31137698, 2019). "MMP16 can promote the invasion and metastasis of melanoma cells by decreasing cell adhesion, inhibiting collagen alignment and inducing lymphatic invasion." (PMID 28422174, 2017). "In melanoma, MMP16 can promote the invasion and metastasis of tumor cells by decreasing cell adhesion, inhibiting collagen alignment and inducing lymphatic invasion." (PMID 29069779, 2017). "By targeting MMP9, MMP12, MMP14, and MMP16, it is conceivable that Estradiol and Calcitriol could disrupt critical pathways involved in melanoma progression, offering a novel and potentially effective approach for combating this aggressive form of skin cancer." (PMID 39493455, 2024). "Similarly, MMP15 and MMP16 were shown to promote invasiveness of tumor cells in 3D fibrin matrices, while, in particular, MMP16 is highly expressed in aggressive melanoma." (PMID 32575583, 2020). "Most of the shared genes (40 genes) were downregulated including MMP16, IGF1R, FLOT1 and CEP19 and are functionally involved in several types of cancers, including melanoma." (PMID 32613561, 2020).
gastric cancer (11 papers, 2012 to 2021). A primary or metastatic malignant neoplasm involving the stomach. "It has been reported that ectopic MMP16 expression can promote migration and invasion of gastric cancer cells and thus cause worse survival outcome in gastric cancer." (PMID 29069779, 2017). "Overexpression of MMP16 can promote migration and invasion of gastric cancer cells and then cause worse long time survival in gastric cancer." (PMID 28422174, 2017). "For instance, MMP16 is overexpressed in gastric cancer and is linked to unfavorable prognosis." (PMID 34730679, 2021). "According to the reports, MMP-16 promotes the migration and invasion of gastric cancer (GC) cells and thus causes worse survival outcome in GC." (PMID 31043859, 2019). "Upregulation of MMP14 and MMP16 (MT3-MMP) is involved in EMT, and associated with the aggressiveness of human ovarian, breast and gastric cancer." (PMID 28399108, 2017). "MMP16 is a downstream of β-catenin gene in human gastric cancer, induction of the MMP16 expression is critical in the Wnt-mediated progression and metastasis in gastric cancer cells, β-catenin itself is also a key regulator in EMT procedure." (PMID 29069779, 2017). "Recent studied demonstrated that MMP16 was highly expressed and correlated with poor prognosis in gastric cancer patients by promoting proliferation and invasion of gastric cancer cells." (PMID 29069779, 2017). "Previous studies have shown that MMP16 enhance the growth and invasiveness of Madin-Darby canine kidney cells and gastric cancer cells." (PMID 22453125, 2012). "In gastric cancer, MMP16 expression was shown to be upregulated by Wnt activation." (PMID 32352029, 2020). "Silence of MMP16 expression significantly decreased the invasion and proliferation capacity of gastric cancer (GC)." (PMID 31137698, 2019). "In gastric cancer, the expression of MMP-14 and MMP-16 was found to be upregulated, thereby promoting EMT through Wnt/β-catenin pathway." (PMID 32366234, 2020).
breast carcinoma (10 papers, 2009 to 2024). "Correlations of LincRNA H19, miR-675, MRP3, HOXA1, and MMP16 with clinicopathological parameters in patients with breast cancer." (PMID 39267845, 2024). "The expression levels of LincRNA H19, miR-675, MRP3, HOXA1, and MMP16 in breast cancer tissues also suggest a strong link with the early onset and types of breast cancer, with MRP3 showing high prognostic value." (PMID 39267845, 2024). "A similar pattern was observed for MMP16, with high expression in 552 breast cancer tissues and low expression in 29, while in the adjacent tissues, high expression was noted in 16 samples and low in 565 samples, indicating significant differences (P < 0.01)." (PMID 39267845, 2024). "Six target genes (FGFR2, RET, ERBB4, SOX2, FN1, and MMP16) were analyzed across breast cancer studies using the cBioPortal to assess genomic alterations." (PMID 36601474, 2022). "These known targets included CEBPα, STK40, and E2F2 which had been shown to be downregulated at mRNA level by miR-31-H in ovarian cancer cells and Frizzled3 (Fzd3) and MMP16 which were repressed at the protein level by miR-31 in MDA-MB-231 breast cancer cells." (PMID 23472152, 2013). "Furthermore, Spearman correlation heatmap analysis revealed a strong positive correlation among the expressions of LincRNA H19, miR-675, MRP3, HOXA1, and MMP16 in breast cancer tissues." (PMID 39267845, 2024). "In addition to the findings on SNPs and LincRNA H19, this study also investigated the expression of MRP3, HOXA1, and MMP16 in breast cancer tissues." (PMID 39267845, 2024). "Due to their solid digesting function, the matrix metalloproteases MMP1, MMP11, MMP14, and MMP16 might confer invasiveness to breast cancer cells through the Zn2+-bound ZEB1." (PMID 36910659, 2023). "MMP16 promotes the migration and invasion of cancer cells in the breast cancer." (PMID 36601474, 2022). "A genetic alteration study of potential target genes revealed MMP16 and ERBB4 as the genes with the highest alterations among the breast cancer samples." (PMID 36601474, 2022). "In conclusion, FGFR2, RET, ERBB4, MMP16, FN1, and SOX2 are potential targets of HON for overcoming TAM resistance in breast cancer." (PMID 36601474, 2022). "In this study, the expression levels of LincRNA H19, miR-675, MRP3, HOXA1, and MMP16 were consistently higher in 581 breast cancer tissues compared to adjacent non-tumor tissues." (PMID 39267845, 2024). "We also analyzed the relationship between the mRNA levels of FGFR2, ERBB4, RET, FN1, MMP16, and SOX2 and tumor stages in breast cancer using GEPIA and found that the levels of FGFR2 were significantly upregulated in stage I and remained stable across stages II–X." (PMID 36601474, 2022). "Moreover, patients with breast cancer having low mRNA levels of RET, MMP16, FN1, and SOX2 had better OS; however, the difference was not significant." (PMID 36601474, 2022). "For examples, in osteosarcoma, colorectal cancer, liver cancer and breast cancer, miR-328-3p overexpression inhibited their migration, invasion, and EMT by directly inhibiting MMP-16, Girdin, Endoplasmic Reticulum Metallo Protease 1 (ERMP1) and CD44, respectively 17, 26-29." (PMID 34659543, 2021). "In addition, patients with breast cancer with low mRNA levels of RET, MMP16, FN1, and SOX2 had better RFS, but this was not significant in the opposite groups (p > 0.05)." (PMID 36601474, 2022). "Ueno and colleagues could not detect MMP-16 (MT3-MMP) in breast cancer tissue using Northern blot analysis, whereas we detected its mRNA in normal and breast cancer tissue by RT-PCR." (PMID 19531263, 2009).
hepatocellular carcinoma (10 papers, 2016 to 2025). A malignant tumor that arises from hepatocytes. "In hepatocellular carcinoma, circ_0001806 regulates miR-193a-5p, which promotes tumor invasion by targeting MMP16." (PMID 40862743, 2025). "For instance, lncRNA ZFAS1 activated the expression of ZEB1, MMP-14 and MMP-16 to promote tumor growth and metastasis by sponging miR-150 in hepatocellular carcinoma." (PMID 31827393, 2019). "Finally, a study suggested that upregulation of circ _ 0001806 could promote the malignant biological behavior of hepatocellular carcinoma (HCC) by regulating MMP 16 expression by inhibiting miR-193a-5p." (PMID 40161373, 2025). "But in hepatocellular carcinoma ZFAS1 serves as an oncogene and promotes cancer metastasis by regulating the expression of related genes such as MMP14 and MMP16." (PMID 32760219, 2020). "ZFAS1 was reported to promote hepatocellular carcinoma metastasis via sponging miR-150 to activate ZEB1, MMP14, and MMP16." (PMID 28983240, 2017). "However, the functions of MMP16 in hepatocellular carcinoma (HCC) remains unknown." (PMID 29069779, 2017). "In hepatocellular carcinoma, ZFAS1 functions as an oncogene in HCC progression by binding miR-150, which adsorbs ZEB1, MMP14 and MMP16 expression, and abrogating the tumor-suppressive." (PMID 29262629, 2017).
lung carcinoma (8 papers, 2014 to 2022). "Genes MMP16 (ENSP00000286614) and MMP19 (ENSP00000313437) belong to the matrix metalloproteinase family that is associated with multiple cancer subtypes, including lung cancer." (PMID 35155435, 2022). "In our study, we found that miR‐558 has binding sites for MMP1, MMP16, MMP17, and MMP24 3'‐UTRs, and only MMP17 and MMP1 were demonstrated to be significantly downregulated by miR‐558 through targeted regulation in lung cancer cells." (PMID 33190405, 2021). "All these results showed that Aiolos overexpression upregulates the Twist/MMP16 expression, and leads to induction of EMT in lung cancer cells." (PMID 30816208, 2019). "The expression of some known targets of miR-31, such as ITGA5, MMP16, and RHOA, was preliminarily examined in miR-31-transfected cells and lung cancer cells." (PMID 24978700, 2014).
osteosarcoma (8 papers, 2016 to 2026). A usually aggressive malignant bone-forming mesenchymal neoplasm, predominantly affecting adolescents and young adults. "Osteosarcoma, a tumor with a predominantly altered osteogenic phenotype, with high expression of MMP16, promotes tumor progression and metastasis." (PMID 41507135, 2026). "This study demonstrated that miR-328-3p can significantly suppress the proliferation, migration and tumor formation, but induce the apoptosis of osteosarcoma cells by directly targeting MMP-16." (PMID 31043859, 2019). "Furthermore, the upregulation of matrix metallopeptidase genes, including MMP1, MMP2, MMP9, MMP11, and MMP16, has been observed in osteosarcoma (OS)." (PMID 38966281, 2024). "MiR-145 suppresses osteosarcoma metastasis via targeting MMP16." (PMID 31137698, 2019). "Thus, miR-328-3p mediates the anti-tumor effect in osteosarcoma via directly targeting MMP-16." (PMID 31043859, 2019).
schizophrenia (8 papers, 2013 to 2022). A major psychotic disorder characterized by abnormalities in the perception or expression of reality. "Recent studies have identified MMP-16 as a schizophrenia risk gene, and MMP-9 and ADAMTS-5 are implicated in schizophrenia and cerebral cavernous malformations, respectively." (PMID 33143303, 2020). "Here, we investigated the schizophrenia risk genes, CNNM2, CSMD1, and MMP16 (Schizophrenia Psychiatric Genome-Wide Association Study [GWAS] Consortium, 2011), and identified alterations in gene expression in the asphyxia rat model for schizophrenia." (PMID 29163023, 2017). "Because, risk variants of CNNM2, CSMD1, and MMP16 are suggested to be involved in one of symptoms of schizophrenia, cognitive impairment." (PMID 29163023, 2017). "Among these five novel schizophrenia risk genes, we focused on Cnnm2, Csmd1, and Mmp16 in this study." (PMID 29163023, 2017). "The schizophrenia-associated locus on chromosome 8q21 is located in the intergenic region upstream of MMP16 gene." (PMID 27058395, 2016). "By integrating the results from different prediction approaches, they identified six top candidates that represent promising causal genes for schizophrenia (CNTN4, GATAD2A, GPM6A, MMP16, PSMA4, and TCF4), including the GPM6A gene." (PMID 35328011, 2022). "Among the 41 prioritized causal genes, CNTN4, GATAD2A, GPM6A, MMP16, PSMA4, and TCF4 represent the most promising causal genes for schizophrenia." (PMID 29540662, 2018). "Molecular mechanisms which mediate the influence of CSMD1 and MMP16 on brain development and the pathobiology of schizophrenia remain unresolved." (PMID 29163023, 2017). "Here, we examined alteration in the novel schizophrenia risk genes, CNNM2, CSMD1, and MMP16 in the brains of rats undergoing cesarean section with or without global hypoxia." (PMID 29163023, 2017). "A recent gene expression profiling study of the superior temporal gyrus showed altered mRNA expression of MMPs and ADAMTSs in schizophrenia, including MMP-16." (PMID 26839720, 2016). "Of note, five (CNTN4, GATAD2A, GPM6A, MMP16, and TCF4) of the top six causal genes are involved in neurodevelopment, further supporting the neurodevelopmental hypothesis of schizophrenia." (PMID 29540662, 2018). "Unfortunately, in our sample sizes, there was no allelic association with schizophrenia for any of the five SNPs [rs7914558 (CNNM2), rs10503253 (CSMD1), rs7004633 (MMP16), rs11191580 (NT5C2) and rs12966547 (CCDC68)] (p > 0.22)." (PMID 24160291, 2013).